FAF1 (Fas associated factor 1)
Description:
Ubiquitin-binding protein. Required for the progression of DNA replication forks by targeting DNA replication licensing factor CDT1 for degradation. Potentiates but cannot initiate FAS-induced apoptosis (By similarity).
Synonyms: hFAF1; UBXD12; UBXN3A; CGI-03; HFAF1s
Tractability: Small molecule: a structure with a bound ligand is known. PROTAC: ubiquitination databases record sites on it; its protein half-life has been measured.
Gene: Protein-coding gene on chromosome 1 (50,437,028 to 50,960,279, reverse strand). Ensembl gene ENSG00000185104.
Subcellular location: Nucleus
Subcellular location (Human Protein Atlas): Nucleoplasm; Acrosome; Equatorial segment; Perinuclear theca
Gene Ontology:
Molecular function: heat shock protein binding; NF-kappaB binding; protein binding; protein kinase binding; ubiquitin binding; ubiquitin protein ligase binding; protein kinase regulator activity; protein domain specific binding
Biological process: Fas signaling pathway; negative regulation of canonical NF-kappaB signal transduction; positive regulation of DNA replication; positive regulation of protein catabolic process; regulation of protein catabolic process; ERAD pathway; positive regulation of apoptotic process; proteasome-mediated ubiquitin-dependent protein catabolic process; ubiquitin-dependent protein catabolic process; regulation of signal transduction
Cellular component: ATPase complex; cytosol; nucleoplasm; nucleus; perinuclear region of cytoplasm; VCP-NPL4-UFD1 AAA ATPase complex; CD95 death-inducing signaling complex; cytoplasm; endomembrane system; nuclear envelope
Genetic constraint (gnomAD): Loss-of-function variants: 7 observed, 29.23 expected, observed/expected ratio (o/e) 0.24, 90% interval 0.14 to 0.45. The upper end of that interval is the gene's LOEUF score, 0.45, which puts it in group 1 of 6, group 1 being the genes least tolerant of losing a copy. Missense variants: 313 observed, 404.12 expected, observed/expected ratio (o/e) 0.77, 90% interval 0.7 to 0.85. Synonymous variants: 123 observed, 142.95 expected, observed/expected ratio (o/e) 0.86, 90% interval 0.74 to 1.
Homologues: Orthologues: chimpanzee FAF1 (99% identical), macaque FAF1 (99% identical), pig FAF1 (98% identical), mouse Faf1 (96% identical), rat Faf1 (96% identical), rabbit FAF1 (93% identical), tropical clawed frog faf1 (84% identical), dog FAF1 (83% identical), zebrafish faf1 (79% identical), guinea pig FAF1 (78% identical), Drosophila melanogaster casp (37% identical), Caenorhabditis elegans ubxn-3 (26% identical), and 1 more. Paralogues in human: FAF2 (20% identical), UBXN7 (14% identical), UBXN8 (11% identical), UBXN10 (8% identical).
Diseases named in the same sentence as FAF1 in open-access papers:
FAF1 is named in the same sentence as 79 diseases in open-access papers, as found by Europe PMC text mining. Sharing a sentence is not in itself a finding about the gene and the disease. The quoted sentences say what the papers report.
breast carcinoma (9 papers, 2014 to 2024). "With regard to hsa_circ_100219 (Circ‐FAF1), our results revealed an AUC of 0.787 (95% CI 0.613–0.962), which showed an acceptable diagnostic efficiency for breast cancer detection." (PMID 34545638, 2021). "We designed the present study to investigate the diagnostic efficiency of serum Circ‐ELP3 and Circ‐FAF1, separately and simultaneously, for diagnosis of patients with breast cancer." (PMID 34545638, 2021). "AKT activation, due to receptor tyrosine kinase transactivation, was shown to inhibit the FAS-associated factor 1 (FAF1)-mediated destabilization of the TGFβ receptor 2 (TβRII) in breast cancer cells." (PMID 34064589, 2021). "In vivo cancer models using cell lines or transgenic mice consistently showed that loss of FAF1 expression is closely associated with breast cancer metastasis." (PMID 28443643, 2017). "Either loss of FAF1 or disassembly of the FAF1/VCP/βTRCP complex via AKT phosphorylation can lead to increased breast cancer metastatic potential." (PMID 28443643, 2017). "In recent years, FAF1-associated studies have also reported that FAF1 is an oncogene with reduced expression in various tumor tissues and cells, such as gastric, cervical and breast cancer and mesothelioma." (PMID 36766229, 2023). "Combined measurement of Circ‐ELP3 and Circ‐FAF1 has a high diagnostic value and may be considered a diagnostic biomarker for breast cancer detection." (PMID 34545638, 2021). "Furthermore, because of high diagnostic efficiency, Circ‐ELP3 and Circ‐FAF1 could be considered as a potential biomarker for breast cancer detection, especially when used in combination." (PMID 34545638, 2021). "For instance, a novel potential biomarker for diagnosing breast cancer was serum Circ‐FAF1/Circ‐ELP3 in one report." (PMID 35792043, 2022). "On the other hand, serum Circ‐FAF1 was seen to be decreased in breast cancer patients than controls (p‐value = 0.001)." (PMID 34545638, 2021). "We also determined the cutoff point of hsa_circ_100219 (Circ‐FAF1) as a biomarker for breast cancer." (PMID 34545638, 2021). "Diagnostic efficiency of serum Circ‐FAF1 is higher than Circ‐ELP3 and both of them have the appropriate diagnostic value for breast cancer detection." (PMID 34545638, 2021). "Briefly, our results revealed the high diagnostic value for combined circRNAs panel, including Circ‐ELP3 and Circ‐FAF1 as a non‐invasive marker, in detection of breast carcinomas." (PMID 34545638, 2021). "By drawing a ROC curve, we determined the diagnostic values of hsa_circ_0001785 (Circ‐ELP3) and hsa_circ_100219 (Circ‐FAF1) for diagnosis of breast cancer." (PMID 34545638, 2021). "It was found that hsa_circ_100219 produces from FAF1 and high level of this circRNA in breast cancer patients can remarkably suppress the proliferation, cell migration, and invasion of cancer cells." (PMID 34545638, 2021). "In especial, FAF1, reported as a tumor suppressor, was found to decrease in many cancers, such as gastric carcinomas and human breast carcinoma." (PMID 30915356, 2019). "In the same database, individuals with breast carcinomas exhibiting higher FAF1 expression had a longer life expectancy than those with tumours exhibiting lower FAF1 expression." (PMID 28443643, 2017). "In summary, AKT antagonizes FAF1 to maintain TβRII stability in metastatic (malignant) breast cancer cells." (PMID 28443643, 2017). "Overall, our data from transgenic mice experiments complement our findings from cell line models and clinical breast cancer samples, strongly supporting the role of FAF1 as a metastasis-suppressing gene via the direct targeting of TβRII." (PMID 28443643, 2017). "Using The Cancer Genome Atlas patient database, we observed that claudin-low breast cancer patients show significant under-expressed FAF1." (PMID 28443643, 2017). "TβRII, P-SMAD2 and P-AKT 473 levels were significantly higher in breast carcinomas, whereas the FAF1 level was significantly lower in cancer tissues compared with normal breast tissues." (PMID 28443643, 2017).
breast carcinoma (continued). "Circ‐FAF1 is decreased in serum sample of patients with breast cancer." (PMID 34545638, 2021). "In conclusion, our results revealed an upregulation in Circ‐ELP3 and, in contrast, a downregulation in Circ‐FAF1 in serum specimens of patients with breast cancer while the levels of these circRNAs showed a decrease and an increase values after treatment, respectively." (PMID 34545638, 2021). "FAF1 overexpression can reduce the metastasis and invasion of breast tumors; thereby, downregulation of FAF1 has a close correlation with increased metastasis in breast cancer." (PMID 34545638, 2021). "Importantly, FAF1 gene loss has been reported in many types of human cancers, suggesting that the tumour-suppressive role of FAF1 is not limited to breast cancer." (PMID 28443643, 2017). "Moreover, both TβRII and P-SMAD2 levels correlated inversely with the FAF1 level in our breast cancer tissue microarray analysis, further corroborating that FAF1 plays an essential role in controlling TβRII and TGF-β signals." (PMID 28443643, 2017). "In addition, knockdown of endogenous FAF1 promoted breast cancer migration and invasion." (PMID 28443643, 2017). "For example, serum levels of circ-FAF1 and circ-ELP3 have been proposed as novel potential biomarkers for breast cancer diagnosis." (PMID 39159001, 2024). "During cancer development, AKT activation mediates FAF1 phosphorylation and subsequent dissociation of FAF1 from the plasma membrane and TβRII, thereby enhancing the cell surface stability of TβRII and activating TGF-β-induced pre-metastatic function in breast cancer cells." (PMID 38365777, 2024). "We uncover a metastasis suppressing role for FAF1 through analyses of FAF1-knockout animals, various in vitro and in vivo models of epithelial-to-mesenchymal transition and metastasis, an MMTV-PyMT transgenic mouse model of mammary tumour progression and clinical breast cancer samples." (PMID 28443643, 2017). "We evaluated in the breast cancer tissue microarray specimens and found the status of AKT activation (p-AKT 473 staining) and FAF1 expression (FAF1 staining) were not correlated, suggesting that these two events might be independent of each other." (PMID 28443643, 2017).
gastric carcinoma (9 papers, 2010 to 2023). A carcinoma that arises from epithelial cells of the stomach. "Consistent with this idea, knocking down expression of the NF-κB activator proteins IKKβ or p65 blocked the ability of H. pylori to down-regulate FAF1 expression as well as trigger other proinflammatory changes linked to gastric cancer." (PMID 28030825, 2017). "We found that Helicobacter pylori, a risk factor for gastric cancer, down-regulated FAF1 expression via NF-κB signaling." (PMID 28030825, 2017). "We performed various subgroup analyses to examine possible associations between FAF1 mRNA expression and clinicopathological features of gastric cancer." (PMID 23304123, 2012). "In the present study, we investigated this and other possible associations between clinical characteristics of gastric cancer and FAF1 expression." (PMID 23304123, 2012). "This study aimed to investigate possible associations between FAF1 expression and aspects of gastric cancer, in particular its clinical characteristics and Helicobacter infection." (PMID 23304123, 2012). "In the present study, we found that expression of both FAF1 mRNA and protein was reduced in gastric cancer tissue, and the level of FAF1 mRNA expression was associated with tumor differentiation, distant metastasis, and clinical stage of tumors." (PMID 23304123, 2012). "Loss of Fas-associated factor 1 (FAF1) may act as a pro-survival signal in diseased cells, but whether this is true in gastric carcinoma remains unclear." (PMID 28030825, 2017). "Single nucleotide polymorphisms in FAF1 are associated with a risk for gastric cancer." (PMID 25861239, 2015). "This may reflect the same processes behind the association between FAF1 downregulation and metastasis, since metastasis is indispensable for aggressive development of gastric cancer." (PMID 23304123, 2012). "They further establish RT-PCR detection of FAF1 mRNA as a reliable and sensitive technique that may prove useful as a novel diagnostic tool for gastric cancer." (PMID 23304123, 2012). "Our findings suggest that reduced FAF1 expression is associated with gastric cancer metastasis." (PMID 23304123, 2012). "It would be interesting to investigate whether MiR-24 helps to explain the observed association between FAF1 gene downregulation and gastric cancer metastasis." (PMID 23304123, 2012). "In fact, FAF1 expression was found to be downregulated in a significant proportion of human gastric carcinomas." (PMID 37999107, 2023). "On the one hand, FAF1 was downregulated in gastric carcinoma, which activated the NF-κB signaling to promote proliferation, infiltration, and lymph node metastasis of gastric carcinoma." (PMID 30915356, 2019). "Fas-associated factor 1 (FAF1) is a pro-apoptotic protein, and its downregulation in gastric carcinoma indicates a poor prognosis." (PMID 29315242, 2018). "Here we report that FAF1 was expressed at low levels in gastric carcinoma tissues and cell lines, and its expression correlated with larger tumors, higher histology grade, higher TNM stage, tumor infiltration, and lymph node metastasis." (PMID 28030825, 2017). "Our laboratory has shown that among gastric cancer patients, FAF1 mRNA levels are lower in tissues positive for H. pylori than in tissues negative for H. pylori." (PMID 28030825, 2017). "FAF1 overexpression in HGC-27 gastric cancer cells induced cell apoptosis and inhibited cell proliferation and growth." (PMID 28030825, 2017). "In previous work, we showed that FAF1 mRNA levels are lower in gastric cancer tissue, especially in poorly differentiated tumors, than in healthy gastric tissue." (PMID 28030825, 2017). "Knock-down of IKKβ or p65 expression in gastric cancer cells reversed H. pylori-induced down-regulation of FAF1 expression and partially blocked H. pylori-induced secretion of inflammatory cytokines TNF-α and IL-8." (PMID 28030825, 2017). "FAF1 was weakly expressed in gastric cancer tissue, but strongly expressed in adjacent tissue or normal gastric tissue." (PMID 28030825, 2017).
gastric carcinoma (continued). "Based on the predictions of proteomic reference pathways and networks in the presence of high FAF1 expression and H. pylori infection, we identified the NF-κB pathway as a potential mediator of the link between FAF1 and gastric cancer." (PMID 28030825, 2017). "Consistent with a protective role of FAF1 against gastric cancer, we found that FAF1 overexpression in gastric cancer cell lines reduced their proliferation and increased apoptosis." (PMID 28030825, 2017). "The expression level of FAF1 mRNA was significantly lower in gastric cancer tissue than in normal gastric mucosa from the same patient (P < 0.05)." (PMID 23304123, 2012). "Expression of FAF1 mRNA and protein was lower in gastric cancer samples than in normal gastric mucosa samples from the same patients." (PMID 23304123, 2012). "The subgroup analyses by metastasis and clinical staging suggest that FAF1 acts as a tumor suppressor and its downregulation contributes to gastric cancer onset and progression." (PMID 23304123, 2012). "FAF1 mRNA expression was significantly lower in stage IV gastric cancer than in stage I+II or IIIA+IIIB (P = 0.004) and also significantly lower in gastric cancer with distant metastasis." (PMID 23304123, 2012). "We also found FAF1 gene expression to be much lower in stage IV gastric cancer than in earlier stages of the disease." (PMID 23304123, 2012). "Expression of FAF1 mRNA and β-actin mRNA was detected in all 40 gastric cancer samples and corresponding normal gastric mucosa samples." (PMID 23304123, 2012). "However, it remains unclear whether the lower protein levels reflect lower levels of FAF1 gene expression, and whether that downregulation is associated with the clinical characteristics of gastric cancer, including the often-observed comorbidity of gastric infection by Helicobacter pylori." (PMID 23304123, 2012). "FAF1 mRNA expression was significantly lower in gastric cancer samples than in the matched normal gastric mucosa samples (0.27 ± 0.12 versus 0.48 ± 0.08, t = 9.209, P < 0.05)." (PMID 23304123, 2012). "To gain deeper insights into the potential role of FAF1 in gastric cancer, we determined levels of FAF1 expression in gastric carcinoma tissues and cell lines, and we examined the effects of FAF1 overexpression on tumor cell proliferation in vitro and tumor growth in vivo." (PMID 28030825, 2017). "We then examined the effects of FAF1 overexpression on key characteristics of gastric cancer cells." (PMID 28030825, 2017). "FAF1 protein expression was measured using immunohistochemistry in samples of gastric cancer tissue, adjacent tissue and normal gastric tissue from 145 patients with gastric cancer." (PMID 28030825, 2017). "Here we investigated the potential involvement of FAF1 in gastric cancer and asked whether NF-κB signaling pathways may mediate this involvement." (PMID 28030825, 2017). "Analysis of gastric cancer tissues suggests that FAF1 expression is quite low in these patients, and that low FAF1 expression may predict patient survival." (PMID 28030825, 2017). "FAF1 mRNA expression showed no obvious association with gender, age, tumor size, infiltration degree, lymph node metastasis or clinical stage below IV in gastric cancer." (PMID 23304123, 2012). "Our work was also unable to identify how FAF1 activity may contribute to gastric cancer onset and progression." (PMID 23304123, 2012). "The recurring loss or downregulation of FAF1 expression observed in certain human and murine cancers suggests that this proapoptotic factor is a tumor suppressor, though FAF1 expression has yet to be analyzed in detail in several other human cancers, including gastric cancer." (PMID 23304123, 2012). "Downregulation of FAF1 expression may be related to the carcinogenesis and progression of gastric cancer, and H. pylori infection during gastric carcinogenesis may downregulate FAF1 expression." (PMID 23304123, 2012).
gastric carcinoma (continued). "Since protein levels are only an indirect measure of gene expression, we wished to probe directly whether FAF1 gene expression was altered during gastric cancer." (PMID 23304123, 2012). "Consequently, increasing FAF1 expression through gene therapy may be effective for treating gastric cancer in the future." (PMID 23304123, 2012). "To extend these in vitro experiments suggesting that FAF1 suppresses gastric cancer progression, we compared the growth of HGC-27/FAF1, HGC-27/NC or HGC-27 tumors in nude mice." (PMID 28030825, 2017). "Using real-time PCR, we measured FAF1 mRNA levels in the HGC-27 and SGC7901 gastric cancer cell lines as well as in the GES-1 normal gastric epithelial cell line." (PMID 28030825, 2017). "It is also possible that FAF1 affects gastric cancer progression through mechanisms that do not depend on NF-κB." (PMID 28030825, 2017). "The negative effect of FAF1 on the NF-κB pathway is a promising therapeutic strategy in human cancers with low FAF1 levels, such as cervical and gastric carcinomas, mantle cell lymphomas, and malignant mesothelioma, which show hyperactive NF-κB activity." (PMID 27754413, 2016). "FAF1 mRNA expression was lower in H. pylori-positive tissue samples than in H. pylori-negative samples from gastric cancer patients (0.18 ± 0.06 versus 0.29 ± 0.12, t = 3.6084, P < 0.05)." (PMID 23304123, 2012). "In the present study, we found evidence for an additional effect of H. pylori infection: FAF1 mRNA expression was lower in H. pylori-positive tissue samples than in H. pylori-negative samples from gastric cancer patients." (PMID 23304123, 2012). "Other studies also have shown that FAF1 expression is reduced in gastric carcinomas compared to non-neoplastic tissue, and there was a significant correlation between FAF1 reduction and the content of signet ring cells in gastric carcinomas." (PMID 20195546, 2010).